NLRP3 (NLR family pyrin domain containing 3)
Diseases named in the same sentence as NLRP3 in open-access papers (continued):
Sharing a sentence is not in itself a finding about the gene and the disease.
schizophrenia (11 papers, 2021 to 2025). A major psychotic disorder characterized by abnormalities in the perception or expression of reality. "In conclusion, we performed a comprehensive analysis to detect the association of NLRP3 with schizophrenia in Han Chinese." (PMID 34956329, 2021). "The human gene encoding NLRP3 (NLRP3) is located on chromosome 1q44, where linkage findings were reported in schizophrenia." (PMID 34956329, 2021). "In this study, we intended to identify the role of gene encoding NLRP3 (NLRP3) in susceptibility to schizophrenia and its clinical features." (PMID 34956329, 2021). "Another aim of this study is to detect the association of NLRP3 functional SNP rs10754558 with schizophrenia." (PMID 34956329, 2021). "NLRP3 is an inflammasome that triggers IL-1, a cytokine that is implicated in the cytokine hypothesis of schizophrenia pathogenesis." (PMID 37139329, 2023). "Thus, we secondly sought to characterize the association of NLRP3 rs10754558 polymorphism with schizophrenia in Han Chinese." (PMID 34956329, 2021). "In the future, the relationship between miR-3653-3p and NLRP3, caspase 1, and IL-1β in patients with schizophrenia is worthy of in-depth research and further validating the potential of miR-3653-3p, NLRP3, caspase 1, and IL-1β as a stable biomarker for schizophrenia in diagnostic experiments." (PMID 37946206, 2023). "In this study, we hypothesized that NLRP3 may confer susceptibility to schizophrenia." (PMID 34956329, 2021). "It is particularly noteworthy that in schizophrenia, iPSC-astrocytes exhibit unique NLRP3-dependent inflammatory characteristics, which are manifested through various cellular functions." (PMID 39859234, 2025). "Peripheral blood mononuclear cell samples from patients with schizophrenia had higher levels of expression of NLRP3, the pro-NLRP3 receptor P2X7, and pro-inflammatory cytokines than samples from the control group." (PMID 40002529, 2025). "The role of NLRP3, Caspase 1, and IL-1β in the pathological process of schizophrenia deserves further investigation." (PMID 37946206, 2023). "The expression of miR-3653-3p, NLRP3, caspase 1, and IL-1β in schizophrenia does show interconnection." (PMID 37946206, 2023). "Previously, differentially expressed prefrontal cortex NLRP3, Caspase 1, and IL-1β have been reported in post-mortem brains of schizophrenia patients." (PMID 37946206, 2023). "The potential use of URB597 for the treatment of schizophrenia has been shown to protect against NLRP3 inflammasome activation." (PMID 35492718, 2022). "For the NLRP3 mRNA expression analysis, 53 drug-naïve patients with first-episode schizophrenia and 56 healthy controls were enrolled." (PMID 34956329, 2021). "Recent studies demonstrated that nod-like receptor pyrin domain-contraining protein 3 (NLRP3) inflammasome is involved in the schizophrenia-like behaviors of MIA model." (PMID 34956329, 2021). "First, we examined the difference of NLRP3 mRNA expression between schizophrenia patients and healthy controls." (PMID 34956329, 2021). "Both LPS and poly(I:C) treatment induced the expression and activation of NLRP3 and IL-1β in the brain of offspring rats showing schizophrenia-like behaviours In vitro studies show higher baseline and LPS-induced Caspase-1, NLRP3, and secreted IL-1β levels in PBMCs from individuals with ASD." (PMID 40713568, 2025). "Bioinformatics previously suggested a link between schizophrenia and NLRP3." (PMID 39859234, 2025). "Although no specific NLRP3 or IL1B gene variants have been directly associated with schizophrenia, autism, or depression, polymorphisms in these genes have been implicated in broader neuroinflammatory processes." (PMID 40713568, 2025). "Increased or abnormal NLRP3 and IL-1 expression along with other specific cytokines including epidermal growth factor (EGF), IL-6, and neuregulin-1 have widely been positively associated with more extreme schizophrenia-like behavior." (PMID 37139329, 2023).
schizophrenia (continued). "Furthermore, the relationship between miR-3653-3p/NLRP3/caspase 1/IL-1β and the pathogenesis of schizophrenia was further verified by in vitro and in vivo experiments." (PMID 37946206, 2023). "Follow-up could be continued in the future, or a comparative study could be conducted between the untreated schizophrenia and chronic schizophrenia patients to detect the expression levels of miR-3653-3p, NLRP3, caspase 1, and IL-1β." (PMID 37946206, 2023). "Finally, we have analyzed only one functional SNP in NLRP3 to evaluate the genetic relationship with schizophrenia." (PMID 34956329, 2021). "Recent preclinical studies have found that activation of NLRP3 when LPS counts may be one of the potential mechanisms driving schizophrenia-like behavior in offspring in MIA model." (PMID 34956329, 2021). "Accordingly, we employed this study to identify the role of NLRP3 in schizophrenia." (PMID 34956329, 2021). "This raises the possibility that SARS-CoV-2 may enhance NLRP3-dependent pyroptosis through the upregulation of HERV-W env, implying that HERV-W env could serve as a potential therapeutic target for both schizophrenia and inflammatory respiratory diseases caused by SARS-CoV-2." (PMID 39859234, 2025). "Finally, we detected miR-3653-3p and NLRP3, Caspase 1 and IL-1β mRNA and explored the relationship between miR-3653-3p and NLRP3, Caspase 1, IL-1β in peripheral blood of schizophrenia; we look forward to searching for stable biomarkers of schizophrenia in peripheral blood." (PMID 37946206, 2023). "Intriguingly, NLRP3/Caspase 1/IL-1β is also involved in the classical pyroptosis pathway, in which IL-1β and IL-18 are activated, and the inflammation is amplified, which may contribute to the pathogenesis of schizophrenia." (PMID 37946206, 2023). "This suggests that NLRP3 SNP rs10754558 is probably not a risk SNP for schizophrenia." (PMID 34956329, 2021). "As such, our findings implied that NLRP3 mRNA level is not a risk factor for schizophrenia." (PMID 34956329, 2021). "However, the relationship of NLRP3 with schizophrenia is not well known." (PMID 34956329, 2021). "In this study, we discovered that HERV-W env promotes pyroptosis by increasing the expression of NLRP3, CASP1, GSDMD and IL1B, potentially representing a novel mechanism by which HERV-W env influences neuronal cell death in patients with schizophrenia." (PMID 39859234, 2025). "Previous research has observed significant upregulation of pyroptosis-related genes, such as CASP1, NLRP3, and IL1B, in the serum of schizophrenia patients." (PMID 39859234, 2025). "A recent report showed that increased expression of NLRP3 and NLRC4, together with high baseline levels of circulating components of IL-18, was observed in the blood of patients with schizophrenia and bipolar disorder compared with healthy controls." (PMID 35546942, 2022). "Another comparative study also showed that peripheral level of NLRP3 is increased in patients with bipolar disorder, but not schizophrenia." (PMID 34956329, 2021). "We also did not observe the difference of NLRP3 mRNA level in brain between schizophrenia and controls." (PMID 34956329, 2021). "We did not observe significant differences of NLRP3 mRNA expression in prefrontal cortex, hippocampus and striatum between schizophrenia patients and healthy controls." (PMID 34956329, 2021). "Thus, our study results also indicated that miR-3653-3p could be involved in the expression of NLRP3, caspase 1, and IL-1β, though NLRP3 was not statistically different between patients with schizophrenia and the controls." (PMID 37946206, 2023).
Schnitzler syndrome (11 papers, 2010 to 2025). A rare, underdiagnosed disorder in adults characterized by recurrent febrile rash, bone and/or joint pain, enlarged lymph nodes, fatigue, a monoclonal IgM component, leukocytosis and systemic inflammatory response. "Activating NLRP3 mutations were identified in patients with Schnitzler’s syndrome, underscoring another possible link between NLRP3 inflammasome activation and MGUS progression to lymphoid neoplasia." (PMID 38397043, 2024). "A recent report describes the NLRP3 V198M variant in a patient with Schnitzler syndrome." (PMID 23421920, 2013). "In patients with Schnitzler’s syndrome, in whom NLRP3 somatic mosaicism has been anecdotally identified, IL-1β secretion is up-regulated." (PMID 37007766, 2023). "Patients with NLRP3 presented similar clinical manifestations to patients with Schnitzler syndrome and both conditions show good response to IL-1 inhibition." (PMID 35411042, 2022). "Unlike other autoinflammatory diseases, Schnitzler syndrome lacks evidence of the gene divergence causing the abnormal activation of NLRP3." (PMID 39859314, 2025). "This was most prominent in treatment‐resistant patients from cohort AOSD#3 who also had higher ASC/NLRP3 specks in comparison with patients with AIDs typically associated with NLRP3 inflammasome activation, such as cryopyrin‐associated periodic syndrome (CAPS) and Schnitzler syndrome." (PMID 39492681, 2025). "However, a genetic analysis failed to establish an association of Schnitzler`s syndrome with germline or somatic mutations in the NLRP3 gene locus except in rare individual cases." (PMID 37063861, 2023). "However, no study has reported a NLRP3 mutation in patients with Schnitzler syndrome." (PMID 35411042, 2022).
skin cancer (11 papers, 2018 to 2025). "Considering the absence of NLRP3 expression in keratinocytes, myeloid cells appear to have a major responsibility for the development of NLRP3 inflammasome-mediated skin cancer development and progression." (PMID 33686176, 2021). "Toll-like receptor-4 (TLR4) and NLR family pyrin domain containing 3 (NLRP3) belong to the family of innate immune receptors and are highly expressed in skin tumors." (PMID 34771569, 2021). "Our results confirm this behavior as silencing NLRP3 could reduce the risk of skin tumors under UVR, as analyzed with skin cancer markers." (PMID 39839625, 2024). "Previous research has shown that the NLRP3 inflammasome, along with interleukin-1, may contribute to the growth of skin cancers." (PMID 39839625, 2024). "In contrast, similar to our results showing the role of NLRP3 inflammasome in myeloid cells in enhancing the metastatic potential, mice with a specific deficiency of ASC in myeloid cells developed reduced skin cancer incidence, showing its pro-inflammatory role in myeloid cells." (PMID 31439870, 2019). "Recent evidence suggested that NLRP3 inflammasome up regulation may aggravate inflammatory responses in skin neoplasms." (PMID 30447690, 2018). "Additionally, knocking out the NLRP3 gene itself led to a decrease in the number of skin tumors." (PMID 39839625, 2024).
viral hepatitis (11 papers, 2017 to 2024). An acute or chronic inflammation of the liver parenchyma caused by viruses. "Studies have shown that the NLRP3 inflammasome plays an important role in various diseases throughout the body, including chronic liver injury (viral hepatitis, non-alcoholic fatty liver disease, etc.)and ALI." (PMID 36834481, 2023). "Several studies suggest that NLRP3 inflammasome is the central player in the pathophysiology of viral hepatitis." (PMID 30319645, 2018). "In addition, a strong correlation is demonstrated between levels of IL-1β and severity of liver inflammation in HBV patients, implying that NLRP3-mediated IL-1β is the potential driving force of HBV-induced viral hepatitis." (PMID 30319645, 2018).
vulvovaginal candidiasis (11 papers, 2012 to 2025). Infection of the vulva and vagina with a fungus of the genus CANDIDA. "Our previous studies have shown that two key hyphae-associated genes, ECE1 and HWP1, were overexpressed during human vaginal candidiasis, and that their upregulation was associated with NLRP3 inflammasome activation, a crucial player in the immunopathogenesis of VVC." (PMID 34946178, 2021). "Gene expression of NLRP3 inflammasome components, in particular caspase 1, by the vaginal EC has been recently reported to be the distinctive hallmark of human vulvovaginal candidiasis, substantiating previous, suggestive genetic or experimental evidence (32, –, 36)." (PMID 29789368, 2018). "Given the crucial role of NLRP3 inflammasome-mediated IL-1β responses during vulvovaginal candidiasis (VVC), we evaluated macrophage responses to C. albicans cells grown in VSM with or without lactic acid." (PMID 39843417, 2025). "In this case, NLRC4 negatively regulates NLRP3 activation in epithelial cells and in a murine model of vaginal candidiasis." (PMID 41249509, 2025). "Beta-glucan is a strong trainer of innate immunity and NLRP3 inflammasome activation that is considered of mechanistic relevance in vaginal candidiasis." (PMID 31803172, 2019). "In this context, treatment with an NLRP3 inhibitor in an experimental model of vulvovaginal candidiasis reduces the ineffective and pathological inflammatory response without altering pathogen abundance." (PMID 30131363, 2018). "Instead, work in recent years has implicated the NLRP3 inflammasome, a danger sensing immune complex, in governing characteristic neutrophil recruitment during human and experimental vaginal candidiasis, as NLRP3−/− mice exhibit reduced immunopathology during infection." (PMID 36581211, 2023). "Genetic polymorphism in innate immunity genes such as mannose-binding lectin (MBL), dectin-1 stop-codon, interleukin 4 (IL-4), and NLRP3 was found to be related to vulvovaginal candidiasis among women with no predisposing factors." (PMID 35832797, 2022). "Transcriptomic analysis of vulvovaginal candidiasis identifies a role for the NLRP3 inflammasome." (PMID 27065992, 2016). "In addition, polymorphisms in the gene coding for NLRP3 have been associated with recurrent vulvovaginal candidiasis, a finding consistent with the notion that deregulated NLRP3 inflammasome activation is associated with both heritable and acquired inflammatory diseases." (PMID 22973279, 2012). "Conversely, in vaginal candidiasis, NLRP3 and NLRC4 were non-redundantly activated." (PMID 41249509, 2025).
airway hyperresponsiveness (10 papers, 2014 to 2025). "Nlrp3-deficient mice exhibited marked protection against airway hyperresponsiveness, leukocyte infiltration, goblet cell metaplasia, and type 2 cytokine production." (PMID 41346596, 2025). "Compared to WT mice, NLRP3-/- mice displayed significantly increased airway hyperresponsiveness (AHR), mucus production, and elevated systemic levels of IL-5 and IL-13." (PMID 41394833, 2025). "In models using OVA, NLRP3-/- mice mostly demonstrated significantly reduced inflammation and airway hyperresponsiveness compared to WT mice." (PMID 41394833, 2025). "Treatment of NLRP3 inflammasome inhibitors significantly attenuated airway hyperresponsiveness, airway inflammation, and reversed T helper 17 (Th17)/regulatory T (Treg) cell imbalance in asthmatic mice." (PMID 35664352, 2022). "Moreover, the proliferation of IL-17-producing ILC3s induced by NLRP3 activation in the lungs was suggested to directly drive airway hyperresponsiveness, which was ameliorated by the blockade of IL-1β49." (PMID 36639716, 2023). "Altogether, existence of wide array of activators of NLRP3 inflammasome suggests that it may be involved in translating metabolic or inflammatory danger signals into metabolic diseases, airway hyperresponsiveness, and even depression." (PMID 27212806, 2016). "Finally, development of airway hyperresponsiveness in response to high-fat diet in mice was shown to be dependent on NLRP3 inflammasome-mediated production of IL-1β and IL-17." (PMID 27212806, 2016). "Activation of the NLRP3 inflammasome with production in the pro-inflammatory cytokine IL-1β and neutrophil extracellular trap (NET) formation drive steroid-resistant neutrophilic inflammation and airway hyperresponsiveness in allergic airway diseases." (PMID 36385161, 2022).
Alcohol (10 papers, 2020 to 2026). "Although the association of miRNA155 and NLRP3 to cognitive function in alcoholism has been recently explored, the correlation between the miRNA155–NLRP3 pathway and alcohol-induced cognitive dysfunction associated with ATOR treatment is still not fully understood." (PMID 35335908, 2022). "Disulfiram is a clinically used anti-alcoholism drug and can inhibit NLRP3 inflammasome activation and pyroptosis." (PMID 41488643, 2025). "At an NLRP3 cut-off of 364.6 pg/ml, the sensitivity for predicting alcohol dependence was 84% and the specificity was 88%." (PMID 34867542, 2021). "In the alcohol dependence group, NLRP3 levels were irrelevant to the Fazekas scale scores, PV scores, DWM scores, and WMV (P > 0.05)." (PMID 34867542, 2021). "To explore the potential biomarker for alcohol dependence, we first detected the expression of NLRP3 and NfL in alcohol dependence patients' serum and found that NLRP3 and NfL levels were higher in alcohol dependence patients than in controls." (PMID 34867542, 2021). "The expression levels of serum NLRP3 in the alcohol dependence group were higher than those in the controls (P = 0.000)." (PMID 34867542, 2021). "In the alcohol dependence group, NLRP3 levels were irrelevant to the MoCA, PSQI, GAD-7, and PHQ-9 scores (P > 0.05)." (PMID 34867542, 2021). "Our study confirmed that the expression of NLRP3 and NfL was higher in alcohol dependence patients than in controls." (PMID 34867542, 2021). "The results indicated that NLRP3 levels were irrelevant to monthly alcohol assumption in the alcohol dependence group (P > 0.05)." (PMID 34867542, 2021). "The expression levels of serum NLRP3 were 377.72 (367.73, 428.90) pg/ml in the alcohol dependence group and 356.35 (352.68, 361.92) pg/ml in the controls." (PMID 34867542, 2021). "ROC curve analysis was used to evaluate the predictive value of NLRP3 and NfL for the diagnosis of alcohol dependence." (PMID 34867542, 2021). "Thus, we speculated whether NLRP3 changed in the serum of alcohol dependence patients and could act as a biomarker." (PMID 34867542, 2021). "The correlations between NLRP3 levels, NfL levels, neuropsychological dysfunction, the degree of WMLs, and white matter volume (WMV) were analyzed in alcohol dependence patients." (PMID 34867542, 2021). "This suggests that although NLRP3 was increased in alcohol dependence patients, it may not be a sensitive marker for assessing the severity of brain damage and prognosing alcohol dependence." (PMID 34867542, 2021).
autoimmune thyroiditis (10 papers, 2018 to 2026). "Serum thyroid peroxidase antibody and thyroglobulin antibody are detected in association with the activation of NLRP3 in autoimmune thyroiditis patients." (PMID 36673016, 2023). "It is reported that Yanghe decoction (a traditional Chinese herbal formulation) can alleviate autoimmune thyroiditis in rat models via downregulating NLRP3 inflammasome and adjusting the imbalance Th17/Treg." (PMID 34707607, 2021). "Accordingly, the aim of this study was to define the relationship of IL-1β +3954 C/T (rs1143634), NLRP3 (rs3806265) T/C, and COX-2 (rs2745557) G/A gene polymorphisms susceptible to autoimmune thyroiditis development." (PMID 34790822, 2021). "Overall, the present study demonstrated that YH alleviated autoimmune thyroiditis in rats by improving NLRP3 inflammasome and immune dysregulation." (PMID 34234669, 2021). "NLRP3 inflammasome plays a crucial role in autoimmune thyroiditis." (PMID 34234669, 2021). "Collectively, the present study indicated that YH treatment significantly protected against autoimmune thyroiditis in EAT rats, which was due to improve NLRP3 inflammasome and immune dysregulation." (PMID 34234669, 2021). "Correlation between NLRP3, NLRP1, NLRC4, absent in melanoma 2 (AIM2), ASC, caspase-1, IL-1β, and IL-18 expression in the autoimmune thyroiditis group." (PMID 29915579, 2018).